TNF (tumor necrosis factor)
Diseases named in the same sentence as TNF in open-access papers (continued):
Sharing a sentence is not in itself a finding about the gene and the disease.
infection (continued). "However, there was no change of TNF-α and IL-6 production in LL37 treated-macrophages in the absence of infection vs. in untreated group, neither in macrophages infected by Aspergillus pre-treated with LL37 or sL37 for an hour vs. by untreated A. fumigatus (data not shown)." (PMID 30842778, 2019). "As there are no head-to-head trials comparing it with the other anti-TNFα inhibitors, the indirect comparison of all five agents suggests that possibly GLM is better tolerated than ADA, CTZ and INF in terms of the risks of serious infection and of discontinuing treatment due to AEs." (PMID 30897745, 2019). "Importantly, those that received Eritoran treatment after PR8 infection but prior to Sp3 superinfection showed a significant decrease (P < 0.05) in both COX2 and IFN-β mRNA expression and a nonsignificant trend toward decreased IL-1β and TNF-α mRNA expression." (PMID 31064834, 2019). "In addition, we showed that PAO1 infection of MPI cells, regardless of the strain, significantly induced the production (mRNA assessment) and release (protein measurement) of IL-1β and TNF-α." (PMID 30083156, 2018). "We found that during the second week post-infection, CYA stimulation significantly increased expression of IL-12, iNOS mRNA and NO when compared to the negative control group and M1 positive control group, and significantly increased expression of TNF-α when compared to the negative control group." (PMID 28821221, 2017). "TNFα treatment at the time of infection increased the total number of both productive and non-productive infections, suggesting that proviruses present in the ‘double negative population’ were shifted to productive (‘yellow’) and non-productive (‘red’) infections (compare DMSO to TNFα treatment)." (PMID 24502247, 2014). "Since the massive infection may directly affect signaling via the tumor necrosis factor receptor 1 (TNFR1), we determine general signaling of this receptor during infection by stimulation with TNF-α in the absence of Chx." (PMID 21799887, 2011). "As the lack of TNFα secretion might contribute to the lack of control of C. burnetii replication in hypoxic bovine macrophages, we treated C. burnetii-infected bovine macrophages with bTNFα and analyzed CFU counts at different time points post-infection under normoxic conditions." (PMID 36793725, 2023). "However, although caspase-8 was cleaved in TNF/SM treated macrophages and neutrophils, caspase-8 was not cleaved following PAO1 infection, indicating that there is no requirement for caspase-8 in GSDMD processing or IL-1β secretion induced by PAO1 infection of neutrophils." (PMID 37730693, 2023). "Given clinical evidence of systemic inflammation in the absence of infection, we hypothesized that the fever was likely a cytokine-mediated phenomenon similar to cytokine release syndrome (CRS) and examined plasma levels of pro-inflammatory cytokines IL-6, TNF-α, and IFN-γ." (PMID 37626859, 2023). "Notably, only a small portion of double-positive (IFN-γ+TNF+) CD8+ T cells were observed in S/M/N/E+CD8+ and RBD+CD8+ T cells among all four groups, indicating that the virus-specific CD8+ T cells induced by breakthrough infection and three-dose inactivated vaccine lacked multiple functions." (PMID 36543767, 2022). "However, terminal plasma levels of MIP-1α and TNF-α were not significantly reduced in SIV/Statin Group 3, indicating that these responses may not be suppressed when statin treatment is initiated during the post-acute phase of infection." (PMID 31882598, 2019). "As we identified no detectable infection driven expansion of vaccine-specific CD4+ T cell populations during the four day culture, we proceeded to investigate whether we could detect infection specific cytokine response (IFN-γ, IL-1β, IL-6, IL-10, IL-12p70 and TNF-α) in the culture supernatant." (PMID 28588268, 2017).
infection (continued). "There was no significant increase in the amount of TNF-α produced by PIC-infected compared to mock-infected controls supporting our hypothesis that other cell types, such as macrophages or dendritic cells, are responsible for the production of TNF-α in PIC infection." (PMID 19814828, 2009).
cancer (7,296 papers, 1987 to 2026). A tumor composed of atypical neoplastic, often pleomorphic cells that invade other tissues. "GSEA and ssGSEA showed that hypoxia, EMT, Myc, glycolysis and TNF-alpha pathways were enriched in the high-risk group, which were known to contribute to the development of cancer." (PMID 40458391, 2025). "Key proinflammatory factors associated with cancer include interleukin (IL)-1β, IL-6, and tumor necrosis factor alpha (TNF-α), along with the transcription factors NF-κB and STAT3." (PMID 41502528, 2025). "Suppressing unregulated inflammatory cytokines (IL-2 and TNF-α) and NO productions from macrophages is one method that can reduce the risk of cancer initiation." (PMID 40022126, 2025). "The regulation of cell death, inflammation, and immune escape in cancer is associated with the TNF signaling pathway." (PMID 41440381, 2025). "The most enriched pathways included those associated with cancer, proteoglycans in cancer, TNF signaling, PI3K-Akt signaling, and resistance to EGFR tyrosine kinase inhibitors." (PMID 40259353, 2025). "The primary objective was to assess the risk of major adverse cardiovascular events or cancer in patients with active RA treated with JAKis or anti-TNF." (PMID 39980606, 2025). "Supercluster 1 was enriched for hypoxia and TNFα signalling - pathways previously implicated in therapy resistance across various cancer types." (PMID 41019980, 2025). "Among the potential risk factors evaluated, only age showed a significant independent association with cancer occurrence during TNF inhibitor therapy." (PMID 41302997, 2025). "When TNF inhibitors were first introduced, concerns arose regarding a potential increase in cancer risk." (PMID 41302997, 2025). "It is nevertheless important to emphasize how, in subgroup analyses, the disparity in the risk of cancer between tofacitinib and TNF inhibitors was more evident among patients aged 65 years or older compared to those in younger age groups." (PMID 40507276, 2025). "Mutated TNF-α can directly contribute to cancer formation, while cytokines such as IL-6, IL-8, and IL-1β stimulate cell proliferation and cervical cancer progression." (PMID 40430101, 2025). "In contrast, TNF inhibitors have been more strongly linked to an increased risk of certain cancers, particularly non-Hodgkin lymphoma." (PMID 41179072, 2025). "Increased expression of TNF-α and IL-6 can be observed in different animal models of cancer pain, which in turn produce persistent cancer pain and associated inflammation, and inhibition of TNF-α and IL-6 signaling reduced nociception." (PMID 39759851, 2025). "Following RIPK1 degradation and loss of scaffold function, cancer cells become more sensitive to therapy-induced TNF and interferon, thereby enhancing the immunostimulatory effects of radiotherapy and immunotherapy." (PMID 41334873, 2025). "Three cytokines, IL-6, TNF-α, and IL-1β, serve as central mediators of cancer-associated hypercoagulability through distinct but overlapping mechanisms." (PMID 40725619, 2025). "The increased risk for cancer seems to relate to the assumption of thiopurines and tumor necrosis factor-α antagonists." (PMID 41008635, 2025). "In line with previous studies, our multivariate regression model confirmed that combination therapy, immunomodulators, and anti-TNFα were associated with increased cancer risk." (PMID 40361323, 2025). "Selenium inhibits the production of pro-inflammatory cytokines such as interleukin-6 (IL-6) and tumor necrosis factor-alpha (TNF-α), both of which are associated with cancer progression." (PMID 40901095, 2025).
cancer (continued). "Anti-TNF agents have also shown potential in preventing colitis-associated cancers in animal models by reducing chronic inflammation." (PMID 39858011, 2025). "In cancer-associated inflammatory states, inflammatory cytokines such as IL-6 and TNF-α not only stimulate the synthesis of CRP but also inhibit the synthesis of albumin, accelerate its degradation, and promote vascular extravasation." (PMID 41415846, 2025). "The bioinformatics analysis of molecular docking proved significant ligand-protein interactions of CBD, THC, and humulene with cancer-associated proteins such as PD-1/PD-L1, TNF-α, and MMP-9." (PMID 40008130, 2025). "Some suggestions have been made that this combination therapy carries a greater cancer risk compared to either anti-TNF or thioprine therapy alone." (PMID 39949431, 2025). "KEGG pathway enrichment of the differentially expressed genes (DEGs) showed that the major DEGs were located in pathways that regulate nicotinate/nicotinamide metabolism, TNF signaling, and microRNAs associated with cancer." (PMID 41391757, 2025). "Cox regression analysis was performed to identify factors associated with cancer occurrence during TNF inhibitor therapy." (PMID 41302997, 2025). "Tumor necrosis factor (TNF)-α is a known activator of p38 MAPK, and elevated TNF-α in the bloodstream associated with cancer is known to activate the p38 MAPK signaling pathway and cause associated neuropathic pain." (PMID 40298791, 2025). "Cancer-associated adipocytes (CAAs), inflammation in adipose tissue, increased IL-6 (interleukin-6) and TNF (tumor necrosis factor) levels, and changes in adiponectin levels are known mechanisms." (PMID 41002580, 2025). "The underlying mechanisms of cancer cachexia are mainly involved in the up-regulation of inflammatory cytokines such as TNF-α and IL-6, which correlate with the imbalance between protein synthesis and protein degradation in muscle cells." (PMID 41226740, 2025). "VEGF also contributes to the TNF signaling pathway, a therapeutic target for diseases associated with immunity and cancer." (PMID 40839671, 2025). "RNA-seq of silencing MESP1 indicated that MESP1 was linked to multiple cancer-associated pathways, including TNF, JAK-STAT, Wnt, and Hippo pathways." (PMID 40610403, 2025). "Long-term investigations are requisite to precisely evaluate the connection between TNF - α antagonist therapy and cancer risk in IBD patients." (PMID 39980561, 2025). "Pro-inflammatory cytokines IL-1β and TNF-α serve as key inflammatory mediators and have been linked to cancer development in numerous studies." (PMID 40699769, 2025). "Due to the fact, that Bregs respond to the TNF-α through inducing cancer tolerance, their enhanced activity is associated with the aggressive course of the cancer, and higher possibility of metastasis." (PMID 40136652, 2025). "Low TNF-α levels present in the inflammatory tumour microenvironment have been implicated in promoting the development, growth, and spread of several cancers, including TNBC." (PMID 41439881, 2025). "We aimed to identify factors associated with cancer during TNF inhibitor therapy and evaluate age-specific risks in Asian patients with AS." (PMID 41302997, 2025). "Inflammatory cytokines such as NF-κB, IL-6, IL-1β, and TNF-α are indicators of inflammation and can be used to assess the severity of cancer-associated myocardial damage." (PMID 40182041, 2025). "Within the cancer-associated module, pathways such as NF-κB and TNF signaling—known to suppress malignancy—exhibited significant downregulation." (PMID 40361356, 2025). "A longitudinal study of 71 cancer survivors suggested that attenuation in IL-1β, IL-6, TNF-α, and IL-10 was associated with either an increased sleep duration or decreased sleep problems." (PMID 41470834, 2025).
cancer (continued). "Immunotherapeutic modalities—including checkpoint inhibitors (PD-1/PD-L1, CTLA-4), CAR-T and CAR-NK cell therapies, cytokine-based treatments (e.g., IL-2, TNF-α), cancer vaccines, and oncolytic viruses—are all susceptible to immune remodeling induced by μg." (PMID 40940834, 2025). "Smoking status (current or former) is a significant risk factor in RA patients because, in combination with certain medications (such as TNFα inhibitors), it can increase the risk of cancer." (PMID 40282506, 2025). "Thiopurines are best avoided in high-risk or cancer-experienced patients, while anti-TNF agents, vedolizumab, and ustekinumab have favorable long-term safety data." (PMID 41228267, 2025). "One of the most well-characterized polymorphisms is TNF-α-308G > A SNP; the wild-type is GG, and the A allele is linked to TNF-α overexpression and unfavorable clinical findings in cancer patients." (PMID 39570546, 2025). "Tumour necrosis factor‐α (TNF‐α) is a known proinflammatory cytokine associated with multiple cancer hallmarks including cancer cell proliferation, angiogenesis, invasion, and metastasis, notably as a prominent NF‐kB activator." (PMID 39592417, 2025). "This perception of increased risk of cancer with tumor necrosis factor inhibitors was also observed in a qualitative study from the United Kingdom that explored the patients’ experiences starting tumor necrosis factor inhibitors." (PMID 40598674, 2025). "Surprisingly, higher TNFα was associated with an increased cancer prevalence, while elevated IL-17 with death risk in the follow-up." (PMID 38051374, 2024). "It is important to highlight that IL-1β, IL-6, IL-8, and TNF-α are directly implicated in cancer development/progression." (PMID 38612423, 2024). "Single nucleotide polymorphisms at position −308 of the TNF-α promoter region have been associated with an increased risk of many types of cancers." (PMID 39451257, 2024). "In a notable study, co-incubation of macrophages, iron oxide NPs, and cancer cells was conducted, which showed an upregulation of M1-associated markers (TNFα and CD86) in macrophages exposed to iron oxide NPs." (PMID 39220871, 2024). "With this link to myelopoiesis, local TNFα has also been shown to potentially be linked to EMH in the context of cancer." (PMID 38443597, 2024). "The evaluation of HWE for various TNF-α polymorphisms shows significant variability influenced by factors such as geography, control source, genotyping methods, and cancer type." (PMID 39243014, 2024). "For instance, we demonstrate that TB-associated NK cells retain the expression of IFN-γ and TNF-α, distinct from NK cells in cancer patients that display general deficiency in both cytokine production and cytotoxic activity." (PMID 39030302, 2024). "Recent studies have reported that inflammatory cytokines, such as TNF-α, are upregulated in brain metastasis and highly associated with the extravasation of cancer cells from blood vessels and their colonization in the brain parenchyma." (PMID 39272945, 2024). "The downregulated DEGs in the comparison, however, were associated with transcriptional mis-regulation in cancer and TNF signaling (KEGG) as well as the positive regulation of transcription by RNA polymerase II (GO:0045944)." (PMID 39205185, 2024). "It is well known that TNF is closely associated with cancer-related inflammation and malignant biological behavior." (PMID 38779100, 2024). "By promoting important cellular mechanisms, such as cell proliferation, migration, and phenotype switch, TNF-α induces its exacerbating effects, which are the underlying cause of many proliferative diseases such as cancer and cardiovascular disease." (PMID 38611112, 2024). "TNF-α to be a prominent effector of immune surveillance which can kill mutated or abnormal cells, including cancer cells, under physiologic conditions." (PMID 38698424, 2024).
cancer (continued). "TNF-α, which is an inflammatory cytokine produced by macrophages and monocytes, is effective in the development of various diseases as well as cancer and can also result in the development of DM by causing pancreatic β-cells to undergo apoptosis." (PMID 38776022, 2024). "TNFα has been associated with the progression and prognosis of different cancer types by perturbing several signaling pathways, e.g., Erk1/2 and NF-κB." (PMID 38166970, 2024). "In February 2021, the FDA issued a warning that tofacitinib (Xeljanz) carries a cancer risk compared to TNF inhibitors in older patients." (PMID 39605908, 2024). "While a link between cancer risk and TNF-α rs361525 polymorphisms has been established, the relationship remains contentious, as conflicting outcomes have been reported across diverse studies." (PMID 38339076, 2024). "Monocytes release various pro-inflammatory cytokines, including interleukins IL-1, IL-6, IL-10, and TNF-α, which are linked to reduced survival and a worse prognosis in patients with malignant tumors." (PMID 39493767, 2024). "Inflammation is closely related to cancer development and progression, and inflammation is primarily associated with changes in the levels of IL-6, TNF-α, and IFN-γ." (PMID 39508039, 2024). "Second, nonsynonymous mutations in the TNF signaling pathway in patients with cancer correlated with reduced efficacy of ICB and lower overall survival." (PMID 38819641, 2024). "A meta-analysis of randomised clinical trials indicates that curcumin effectively reduces TNF-α levels, a pro-inflammatory cytokine linked to chronic inflammation and various cancers." (PMID 39816400, 2024). "When these four pro‐inflammatory factors were added to cancer cells, TNF‐α was the only cytokine to cause a decrease in proliferation alongside an increase in migration." (PMID 37967351, 2024). "Specifically, polymorphisms in the TNF-α gene have been identified as risk factors for several cancers, including breast, gastric, and hepatocellular carcinomas, as evidenced by meta-analyses." (PMID 39243014, 2024). "A meta-analysis of trial databases also showed an increased risk of cancer after anti-TNF treatment in RA patients." (PMID 39120313, 2024). "It has been demonstrated that macrophage-secreted cytokines like tumor necrosis factor (TNF) and interleukins activate cancer-associated pathways such as NF-κB in pulmonary epithelial cells." (PMID 38474119, 2024). "Serum CRP can cause systemic inflammation by secreting various pro-inflammatory cytokines, such as IL-1, IL-6 and TNF-α, resulting in the gradual loss of important protein components in host, leading to the death of cancer patients." (PMID 38184747, 2024). "Higher serum concentrations of TNFα characterize the SSc patients, with the highest values associated with cancer." (PMID 38051374, 2024). "Inflammatory cytokines, such as TNF-α and IL-6, are elevated in HF and have been implicated in promoting cancer cell proliferation and survival." (PMID 39346905, 2024). "TNF, also known as tumor necrosis factor, acts as both an inhibitor and a cytokine closely associated with cancer, playing a role in cancer cell growth, proliferation, invasion, and metastasis." (PMID 38486102, 2024). "TNF-α signaling is associated with a high rate of metastasis and recurrence owing to the residual population of cancer stem cells (CSCs)." (PMID 39135097, 2024). "We measured IL-6, TNFα, and IL-1β, which are risk factors for cancer development and are also involved in HIV-1 pathogenesis." (PMID 38166062, 2024). "It releases active forms of the primary inflammatory cytokine tumor necrosis factor (TNF) and cancer-implicated epidermal growth factor (EGF) family growth factors." (PMID 38781971, 2024).